MMP2 (matrix metallopeptidase 2)
Description:
Ubiquitinous metalloproteinase that is involved in diverse functions such as remodeling of the vasculature, angiogenesis, tissue repair, tumor invasion, inflammation, and atherosclerotic plaque rupture. As well as degrading extracellular matrix proteins, can also act on several nonmatrix proteins such as big endothelial 1 and beta-type CGRP promoting vasoconstriction. Also cleaves KISS at a Gly-|-Leu bond. Appears to have a role in myocardial cell death pathways. Contributes to myocardial oxidative stress by regulating the activity of GSK3beta. Cleaves GSK3beta in vitro. Involved in the formation of the fibrovascular tissues in association with MMP14. PEX, the C-terminal non-catalytic fragment of MMP2, possesses anti-angiogenic and anti-tumor properties and inhibits cell migration and cell adhesion to FGF2 and vitronectin. Ligand for integrinv/beta3 on the surface of blood vessels. [Isoform 2]: Mediates the proteolysis of CHUK/IKKA and initiates a primary innate immune response by inducing mitochondrial-nuclear stress signaling with activation of the pro-inflammatory NF-kappaB, NFAT and IRF transcriptional pathways.
Synonyms: MMP-2; CLG4A; TBE-1; CLG4; MMP-II; MONA
Tractability: Small molecule: a drug acting on it is in phase 2 or 3 trials; a structure with a bound ligand is known; a high-quality ligand is known; it has a high-quality binding pocket; it belongs to a druggable protein family. Antibody: UniProt places it where antibodies can reach, with high confidence; its Gene Ontology location is reachable by antibodies, with high confidence; UniProt predicts a signal peptide or a membrane-spanning region. PROTAC: a small molecule that binds it is known.
Target class: Metallo protease; Metallo protease M10A subfamily; Metallo protease MAM clan; Protease; Enzyme
Chemical probes: PD082578
Gene: Protein-coding gene on chromosome 16 (55,389,700 to 55,506,691, forward strand). Ensembl gene ENSG00000087245.
Subcellular location: Secreted, extracellular space, extracellular matrix (Isoform 1); Membrane; Nucleus; Cytoplasm (Isoform 2); Mitochondrion
Subcellular location (Human Protein Atlas): Vesicles; Predicted to be secreted
Pathways (Reactome):
Extracellular matrix organization: Activation of Matrix Metalloproteinases; Collagen degradation; Degradation of the extracellular matrix
Signal Transduction: Extra-nuclear estrogen signaling; MAPK6/MAPK4 signaling
Developmental Biology: EPH-ephrin mediated repulsion of cells
Immune System: Interleukin-4 and Interleukin-13 signaling
Metabolism of proteins: Regulation of Insulin-like Growth Factor (IGF) transport and uptake by Insulin-like Growth Factor Binding Proteins (IGFBPs)
Gene Ontology:
Molecular function: endopeptidase activity; metalloendopeptidase activity; metallopeptidase activity; protein binding; serine-type endopeptidase activity; zinc ion binding; fibronectin binding; peptidase activity
Biological process: cell migration; cellular response to UV-A; collagen catabolic process; endodermal cell differentiation; extracellular matrix disassembly; negative regulation of metallopeptidase activity; positive regulation of vascular associated smooth muscle cell proliferation; proteolysis; trophoblast cell migration; ephrin receptor signaling pathway; extracellular matrix organization; response to amyloid-beta; response to hypoxia; tissue remodeling; angiogenesis; cellular response to cytokine stimulus; cellular response to estradiol stimulus; cellular response to fluid shear stress; cellular response to interleukin-1; female pregnancy; heart development; luteinization; macrophage chemotaxis; negative regulation of cell adhesion; negative regulation of vasoconstriction; and 20 more
Cellular component: extracellular matrix; extracellular region; protease inhibitor complex; cytoplasm; membrane; mitochondrion; nucleus; plasma membrane; sarcomere
Genetic constraint (gnomAD): Loss-of-function variants: 39 observed, 77.94 expected, observed/expected ratio (o/e) 0.5, 90% interval 0.39 to 0.65. The upper end of that interval is the gene's LOEUF score, 0.65, which puts it in group 2 of 6, group 1 being the genes least tolerant of losing a copy. Missense variants: 803 observed, 921.6 expected, observed/expected ratio (o/e) 0.87, 90% interval 0.82 to 0.92. Synonymous variants: 367 observed, 355.94 expected, observed/expected ratio (o/e) 1.03, 90% interval 0.95 to 1.12.
Homologues: Orthologues: chimpanzee MMP2 (99% identical), macaque MMP2 (99% identical), mouse Mmp2 (96% identical), dog MMP2 (96% identical), rat Mmp2 (95% identical), guinea pig MMP2 (95% identical), pig MMP2 (90% identical), rabbit MMP2 (84% identical), tropical clawed frog mmp2 (79% identical), zebrafish mmp2 (71% identical), Caenorhabditis elegans zmp-3 (19% identical), Caenorhabditis elegans zmp-4 (18% identical), and 3 more. Paralogues in human: MMP9 (47% identical), MMP13 (33% identical), MMP3 (32% identical), MMP10 (31% identical), MMP1 (30% identical), MMP12 (29% identical), MMP20 (29% identical), MMP8 (29% identical), MMP27 (28% identical), MMP25 (28% identical), MMP16 (28% identical), MMP24 (28% identical), and 11 more.
Diseases named in the same sentence as MMP2 in open-access papers:
MMP2 is named in the same sentence as 906 diseases in open-access papers, as found by Europe PMC text mining. Sharing a sentence is not in itself a finding about the gene and the disease. The quoted sentences say what the papers report.
breast cancer (894 papers, 2003 to 2026). A primary or metastatic malignant neoplasm involving the breast. "As is observed, the present study reported a significant association of MMP2 rs2285053 polymorphism with breast cancer risk in four genetic models, including the additive model 1, the dominant model, the overdominant model, and the allele model." (PMID 40735254, 2025). "MMP-2 is a type IV collagenase; its expression in breast cancer cells is associated with a worse prognosis." (PMID 41373503, 2025). "To date, only three studies have investigated the association between rs2285053 in MMP2 and breast cancer risk." (PMID 40735254, 2025). "Increased MMP2/MMP9 levels in the blood were associated with a considerably reduced chance of survival for females with breast cancer." (PMID 40735254, 2025). "A gene signature associated with human breast cancer lung metastasis was identified and included key markers such as tenascin C and MMP-2." (PMID 39682261, 2024). "Our results disclosed that higher expression of PTGS2/ESR2/EGFR/JUN/MMP2 genes’ signature associated with the most aggressive breast cancer subtypes donating by basal breast cancer (P < .00001) and the ER-negative breast tumors ( P < .00001)." (PMID 39707884, 2024). "We then consolidated an OPN pathway and upregulated gene signatures from our findings (Spp1, Timp3, Col11a1, Mmp9, Mmp2, Fn1, Cd44, and Il-4) to interrogate how their predicted activity is associated with relapse-free survival in breast cancer patients." (PMID 39448577, 2024). "Activated MMP-2 were highly expressed in breast cancers and were associated with invasive potential." (PMID 36639546, 2023). "It has been reported that STAT3-mediated breast cancer cell metastasis is associated with the upregulation of vimentin, MMP-2, and MMP-9." (PMID 37836626, 2023). "In colon and MCF-7 and MDA-MB-231 breast cancer cells, this compound caused an increase in MMP-2, MMP-7, and MMP-9 levels as well as cell migration." (PMID 36310188, 2023). "Several studies have investigated the association between clinicopathological features of breast cancer with MMP-2, MMP-9, and matrix metallopeptidases − 11 (MMP-11) expression." (PMID 37798646, 2023). "Some studies have shown that tumoral MMP-2 expression is significantly associated with shorter survival in patients with breast cancer." (PMID 36741729, 2022). "Higher expression of Mmp2 and Mmp9 was also associated with histological grade, higher clinical stage, and predicted poor survival of breast cancer patients." (PMID 36612044, 2022). "Specifically, the α3β-integrin-tetraspanin protein complex has been linked to an invasive phenotype of the MDA-MB-231 breast cancer cell line, via the activation of MMP-2 and signaling pathways controlling the cytoskeleton." (PMID 36143328, 2022). "Breast cancer cell migration and invasion was increased by activation of the client MMP2 following a coordinated action of eHsp90 and associated chaperones and co-chaperones including Hsp70, Hsp40, HOP, and p23." (PMID 36060252, 2022). "In a breast cancer cell model pan-HDAC inhibitor treatment led to hyperacetylated eHsp90 that bound MMP2 and was associated with increased invasiveness in cell-based assays." (PMID 36060252, 2022). "To establish the role of sphingolipids in breast cancer metastasis, we analyzed the associations of MMP-2 and MMP-9 with SPHK1 and CERK expression." (PMID 36309544, 2022). "A meta-analysis comprised of 41 studies and 6517 breast cancer patients demonstrated that a higher expression of Mmp2 and Mmp9 in tumor cells of patients was strongly associated with larger tumors and metastasis to lymph nodes and distant organs." (PMID 36612044, 2022). "In particular, high tumoral MMP-2 expression was significantly correlated with an increased risk of bone metastasis in breast cancer." (PMID 36741729, 2022).
breast cancer (continued). "To explore the mechanisms underlying the regulation of migration and invasion in breast cancer cells following sauchinone treatment, we first screened representative MMPs (MMP2, MMP3, MMP9, and MMP13) via immunoblotting analysis." (PMID 34643237, 2021). "MMP-14 has been shown to be regulated in breast cancer, where it is reported to activate MMP2 that is, in turn, associated with increased risk of malignancy and metastasis." (PMID 34314429, 2021). "MMP-9 and MMP-2 are implicated in the metastasis of breast cancers via degradation of the ECM and promotion of tumor vascularisation." (PMID 33968759, 2021). "HDAC2 enables the motility of breast cancer cells by upregulating Matrix Metalloproteinase 2 (MMP2) and N-cadherin and HDAC3 associates with Epidermal Growth Factor Receptor (EGFR) and c-Src to promote breast cancer cell invasion." (PMID 33803458, 2021). "IL-1β is also linked to the migration and invasion in breast cancer, for example through loss of E-cadherin and an increase in MMP-2 and MMP-9, leading to a degradation of the extracellular matrix." (PMID 34944905, 2021). "Complementarily, Rsv decreased other genes associated with the EMT, such MMP9 and MMP2, which are involved in the aggressiveness and invasiveness of Doxo-resistant breast cancer." (PMID 33204396, 2020). "MMP-2 is also associated with the development, aggressiveness, and overall survival rate in breast cancer." (PMID 32751899, 2020). "A study conducted in Mexico reported a strong association between the MMP-2 c.-1586C>T polymorphism (rs243865) and breast cancer risk." (PMID 30781715, 2019). "In breast cancer patients, the level MMP-2 and MMP-9 are overexpressed which is associated with a shortened relapse-free survival." (PMID 30518369, 2018). "While these studies show a correlation between MMP-2 and breast cancer aggressiveness, preclinical animal models have also defined causal roles for MMP-2 in promoting invasion and metastasis via ECM degradation and angiogenesis." (PMID 29874869, 2018). "While clear functions for cancer-cell-derived MMP-2 are implicated in breast cancer progression and metastasis, stromal-derived MMP-2 has also been shown to play key roles in the disease." (PMID 29874869, 2018). "We conclude that in the PyVmT model, the majority of MMP-2/-9 activity in mammary tumors is associated with host macrophages recruited into the tumor rather than that produced by the tumor cells themselves." (PMID 30248101, 2018). "In order to grow successfully, breast cancer cells must become resistant to apoptosis and proliferate, and MMP-2 has been implicated in these processes." (PMID 29874869, 2018). "Using a minimum threshold of five mutated samples (test set) and focusing initially on breast cancer, we found that MMP2 predictions were strongly associated with predictions for PIK3CA (0.47), PTEN (0.49), and AKT1 (0.28), which operate via the same pathway." (PMID 29322935, 2017). "Hypoxia induces increased expression and activity of MMP-2 and MMP-9 through a HIF-1-dependent process, and increased levels of MMP-2 in breast cancer biopsies were associated with poor prognosis." (PMID 27706047, 2016). "Among others, MMP-9 is the main MMP to digest basement membrane collagen and MMP-2 is found to be positively associated with breast cancer progression." (PMID 27110769, 2016). "For example, the expression of MMP9, MMP13 and MMP14 all correlated with poor survival in patients with breast cancer, and expression of MMP1 and MMP2 was associated with highly aggressive breast cancer that metastasizes rapidly to the lung." (PMID 26956475, 2016). "Meta-analysis of the association between MMP-2 overexpression and clinic-pathological features of breast cancer." (PMID 25816052, 2015). "High expression of MMP-9 and MMP-2 were associated with lymph node metastasis as well as with poorer survival in breast cancer." (PMID 25888829, 2015).
breast cancer (continued). "The loss of miR-106b therefore accounted for increased MMP-2 expression, leading to enhanced migration and invasion of breast cancer cells." (PMID 24670365, 2014). "In gain of function studies, we find that PIAS1 acts in a SUMO E3 ligase-dependent manner to suppress the ability of TGFβ to promote activation of the matrix metalloproteinase 2 (MMP2) and associated invasive behavior of breast cancer cells." (PMID 25594015, 2014). "MMP1 and MMP2 were associated with many aspects of breast cancer prognosis including unique associations with ER/PR tumor status as well as with survival." (PMID 23696797, 2013). "Polymorphisms in MMP2 have been associated with breast cancer risk specifically in the Shanghai Breast Cancer Study, a large case-control study of over 6000 Chinese women, and in a small study of 90 cases and 96 controls in Mexico." (PMID 23696797, 2013). "As MMP2/9 have been more specifically implicated in breast cancer metastasis we also measured these." (PMID 24098477, 2013). "While most associations were modest, multiple polymorphisms in MMP1 and MMP2 were associated with breast cancer risk overall and with ER+ tumors." (PMID 23696797, 2013). "Breast cancer cells have been demonstrated to be closely associated with the expression of uPA, MMP-2, MMP-9 and VEGF." (PMID 24137293, 2013). "MMP1 [4 single nucleotide polymorphisms (SNPs)] and MMP2 (2 SNPs) were associated with breast cancer overall." (PMID 23696797, 2013). "As members of the metalloproteinase family, MMP-2 and -9 are associated with breast cancer invasion and metastasis, as well as bone destruction." (PMID 24137293, 2013). "MMP2 rs243845 was significantly associated with breast cancer risk among post-menopausal women only (OR 0.73, 95% CI 0.61,0.88 for TT vs CC genotypes; adjusted p for interaction = 0.036)." (PMID 23696797, 2013). "MMP2 rs243865 (−1306C>T) was associated with significantly higher risk of breast cancer in a study of 90 breast cancer cases from Mexico (OR 2.15 95% CI 1.1,4.1), especially among women younger than 50 years of age." (PMID 23696797, 2013). "Tumour expression of MMP-2 has been associated with poor prognosis in colorectal, gastric, ovarian, and breast cancer." (PMID 23216739, 2012). "In association with TIMP-2, MMP-14 is involved in MMP-2 activation, being also correlated with breast cancer progression." (PMID 22260435, 2012). "An association between α5β3 integrin and MMP-2 activation was demonstrated in melanoma and breast cancer cells." (PMID 20492722, 2010). "Recent studies have shown that ERK-specific inhibitors cause a decrease in the expression of MMP2 in breast cancer brain metastases." (PMID 19292920, 2009). "In this respect, a correlation between a high expression of MMP-2 and reduced survival in breast cancer patients as well as an association of the tumor grade with increased levels of MMP-9 in breast cancer tissue was described." (PMID 19531263, 2009). "Co-culture of macrophages with breast cancer cells results in a marked increase in tumour cell invasion, which is associated with upregulation of MMP-2 and MMP-9." (PMID 19014637, 2008). "The MMP-2 protein found in breast carcinoma tumour cells was here shown to be associated with a shortened recurrence-free survival or relative overall survival (P=0.03)." (PMID 14520459, 2003). "This study is aimed at defining the possible favourable effect of the MMP-2 negativity in primary breast carcinoma in high-risk patient groups while confirming the MMP-2 immunoreactive protein as a prognostic factor also in node-negative breast carcinoma." (PMID 14520459, 2003). "The current study concludes that MMP2 (rs2285053) is associated with an increased risk of breast cancer, while MMP9 (rs3787268) polymorphisms may be correlated with a reduced risk of breast cancer in Bangladeshi females." (PMID 40735254, 2025).